EGFR (epidermal growth factor receptor)
Diseases named in the same sentence as EGFR in open-access papers (continued):
Sharing a sentence is not in itself a finding about the gene and the disease.
adenocarcinoma (continued). "ALK rearrangement was identified in 2 patients (1.0%) from the test set and both adenocarcinomas were negative for EGFR and KRAS mutations." (PMID 23936355, 2013). "EGFR-mutated adenocarcinomas had a higher female prevalence in never smokers compared with that in heavy smokers (P<0.001)." (PMID 24179496, 2013). "In multivariate analyses, EGFR mutations found in female East Asian never-smokers with adenocarcinoma were associated with an objective response." (PMID 23817662, 2013). "In our study, none of the patients with EGFR mutation had an ALK gene rearrangement (data not shown), which is in line with the literature, indicating that EML4-ALK fusion tends to occur in adenocarcinomas lacking EGFR mutation." (PMID 23484153, 2013). "Selection by backgrounds, Asian origin, adenocarcinoma histology, and light or nonsmoking resulted in an EGFR mutation-rich population at a rate of 60 % (261 EGFR-mutated patients/437 patients evaluated)." (PMID 23361373, 2013). "Generally, women and non-smoking patients with adenocarcinoma have a relatively high probability of EGFR mutations." (PMID 24205245, 2013). "In crude analyses, women, patients who were younger, never smokers, and those with adenocarcinoma histology were significantly more likely to test positive for EGFR mutations." (PMID 23468851, 2013). "Since most patients with EML4-ALK fusions do not exhibit EGFR mutations, a specific molecular subset of adenocarcinomas is characterized by EML4-ALK fusion." (PMID 23341890, 2013). "We confirmed that the EML4-ALK positive adenocarcinoma has no mutations in exons 18, 19, 20, 21 of EGFR gene (data not shown)." (PMID 23617234, 2013). "Out of the 44 adenocarcinoma patients, 19 were treated with EGFR-TKIs following WBRT." (PMID 24649230, 2013). "TTF-1 positive adenocarcinomas showed an EGFR mutation more often than those who were TTF-1 negative (26/150 vs 1/50, Fisher's exact 2-sided test, p = 0.01)." (PMID 23922984, 2013). "EGFR-mutated adenocarcinomas displayed a larger number of copy number alterations and recurrent amplifications, a higher fraction of total loss-of-heterozygosity, higher genomic complexity, and a more distinct expression pattern than EGFR-wild type adenocarcinomas." (PMID 24205279, 2013). "For example, somatic mutations of the epidermal growth factor receptor (EGFR) are especially prevalent in adenocarcinomas among never smokers, females, and those with Asian ethnicity." (PMID 23289484, 2013). "EGFR mutations are more likely to occur in patients of Asian origin, who are female, never-smokers and have adenocarcinoma." (PMID 23620765, 2013). "It is recommended that EGFR mutation analysis of NSCLC including adenocarcinoma and nonadenocarcinoma should be a routine molecular test in China after lung resection." (PMID 24351833, 2013). "Patients with clinical features such as female, never smoker, adenocarcinoma, Asian ethnicity and EGFR mutation positive had more pronounced PFS benefit." (PMID 23555654, 2013). "In the current study, EGFR expression was found in nearly half of adenocarcinomas." (PMID 22792097, 2012). "Asian ethnicity, female gender, nonsmoking history, and adenocarcinoma histology were associated with better responsiveness to EGFR TKIs in several clinical studies." (PMID 22992338, 2012). "The subgroup of nonsmokers with adenocarcinoma or adeno-squamous-cell carcinoma without EGFR mutations harbor a frequency of HER2 mutations of 14.1% (11/78)." (PMID 22928112, 2012). "EGFR mutations are more common in non-smoking East Asian females and those with adenocarcinoma histology (95% were found in adenocarcinomas)." (PMID 23109866, 2012). "In a subgroup of non-smokers with adenocarcinoma, EGFR was the most frequently altered gene, with a mutation rate of 49.8%, followed by EML4-ALK (9.3%), PTEN (9.1%), PIK3CA (5.2%), c-Met (4.8%), KRAS (4.5%), STK11 (2.7%), and BRAF (1.9%)." (PMID 22768234, 2012).
adenocarcinoma (continued). "The fusions occurred predominantly in adenocarcinomas from never smokers and were mutually exclusive of mutations in EGFR, KRAS, and ALK." (PMID 22928112, 2012). "No study on EGFR mutation in adenocarcinoma of esophagogastric junction has been reported so far as we known." (PMID 22252115, 2012). "Because the presence of EGFR mutations in general is predictive of responsiveness to EGFR tyrosine kinase inhibitors, adenocarcinoma or NSCLC not otherwise specified should be tested for such alterations." (PMID 22236606, 2012). "Our results are consistent with previous studies where ALK rearrangements have been largely (but not completely) restricted to adenocarcinomas that lack EGFR or KRAS mutations." (PMID 23198868, 2012). "EGFR mutations are mostly observed in lung tumors, and curiously they are more prevalent in Asian women diagnosed with adenocarcinoma who never smoked." (PMID 23207070, 2012). "Classical EGFR mutations occur preferentially in specific subsets, such as patients with adenocarcinoma histology, never smokers, those with East Asian ethnicity, and female patients." (PMID 22928112, 2012). "EGFR mutations in these populations are associated with female patients, patients who have never smoked and patients with an adenocarcinoma." (PMID 22528563, 2012). "Using SARMS, we found no additional EGFR mutations among these EBUS-derived adenocarcinoma aspirates." (PMID 21949883, 2011). "Patients enrolled shared several key clinical features with EGFR-mutated patients (adenocarcinoma histology and nonsmoking history)." (PMID 21444946, 2011). "Woman, non-smoker and adenocarcinoma showed a higher percentage of EGFR mutations (60%, 55% and 48%, respectively; P < 0.05)." (PMID 21414214, 2011). "It is well known that EGFR mutations are predominantly found in patients with adenocarcinoma, history of never-smoking, and female gender." (PMID 22091430, 2011). "On multivariate analysis, N3 nodal status and PMME, along with adenocarcinoma and a history of never-smoking, remained significant factors for EGFR mutations." (PMID 22091430, 2011). "EGFR mutations were predominant in never-smokers (P < .001), patients with adenocarcinomas (P < .001), and female patients (P < .001)." (PMID 22091430, 2011). "It has been demonstrated that EGFR mutations are frequently found in females, patients with adenocarcinomas, and never-smokers." (PMID 22091430, 2011). "A two-sided chi-square test showed that gender (female), smoking status (never smoker), histology (adenocarcinoma), and chest CT findings (normal) were significantly associated with the presence of an EGFR mutation." (PMID 22191026, 2011). "EGFR mutations were identified in 11 of 89 (12.3%) adenocarcinomas and 13 of 110 (12%) non-squamous histology." (PMID 21949883, 2011). "Adenocarcinomas (P < .001), female gender (P < .001), and never-smokers (P < .001) were positively related with the presence of EGFR mutations." (PMID 22091430, 2011). "As first-line treatment of patients with known EGFR mutation or clinically selected (Asians with adenocarcinoma and non-or light smoking history), PF00029804 showed encouraging efficacy, with 6 month-PFS rate of 67% (85% in those with EGFR mutation)." (PMID 21444946, 2011). "The predominance of EGFR mutations in never-smokers, patients with adenocarcinomas, and females was also observed." (PMID 22091430, 2011). "EGFR mutations have been found more frequently in non-smoking East Asian women with adenocarcinoma with bronchioalvelar features." (PMID 20459863, 2010). "K-RAS mutations present more commonly in adenocarcinomas from elderly patients and heavy smokers who have been identified as a group unlikely to respond to EGFR TKIs." (PMID 21165163, 2010).
adenocarcinoma (continued). "Activating mutations in the epidermal growth factor receptor (EGFR), affecting hotspots within exons that code for the tyrosine kinase domain, can be found in 10-40% of NSCLC patients, mostly in adenocarcinomas, with the higher frequency observed in Asian patients." (PMID 21167064, 2010). "Several clinical features were found to be associated with increased response rates to EGFR TKIs, including Asian ethnicity, non-smoking history, female gender and adenocarcinoma histology." (PMID 20637128, 2010). "The EML4-ALK fusion was associated with non-smokers (P = 0.03), younger age of onset (P = 0.03), and adenocarcinomas without EGFR/KRAS mutations (P = 0.04)." (PMID 20624322, 2010). "The EML4-ALK fusion gene was present at a high frequency in Chinese NSCLC patients, particularly in those with adenocarcinomas lacking EGFR/KRAS mutations." (PMID 20624322, 2010). "EGFR mutations are more common in NSCLC from tumors with adenocarcinoma histology, women, Asians, and never smokers with widely varying frequencies dependent on the population examined." (PMID 21165163, 2010). "Further analysis revealed that EML4-ALK was present at a frequency of 16.13% (10/62) in patients with adenocarcinomas, 19.23% (10/52) in never-smokers, and 42.80% (9/21) in patients with adenocarcinomas lacking EGFR and KRAS mutations." (PMID 20624322, 2010). "A high frequency of the EML4-ALK fusion gene was present in Chinese patients with NSCLC, particularly in patients with adenocarcinomas without EGFR/KRAS mutations." (PMID 20624322, 2010). "Interestingly, they also found that EGFR pathway gene amplification was more frequent in the adenocarcinoma subtype of NSCLC." (PMID 19238210, 2009). "Molecular markers such as EGFR high gene copy or EGFR mutations and clinical characteristics such as adenocarcinoma, female sex, never smoking, and Asian ethnicity appear to be associated with a higher likelihood of response to an egfr-tki." (PMID 19229369, 2009). "EGFR mutations were exclusively found in adenocarcinoma histology and in never smokers or individuals with low smoke exposure (<15 PYR)." (PMID 19238210, 2009). "EGFR mutations are independently associated with adenocarcinoma histology, East Asian ethnicity, never smoking status and female gender." (PMID 19238210, 2009). "The EGFR mutations were significantly more frequent in women (P⩽0.02), in patients with adenocarcinoma (P=0.001) and in people who had never smoked (P<0.001)." (PMID 18283321, 2008). "In the screening process for the present study, EGFR mutations were significantly more frequent in women, patients with adenocarcinoma and those who had never smoked." (PMID 18283321, 2008). "They showed that female never smokers with adenocarcinoma (three clinical predictors) had a 33% response rate, whereas patients with a positive EGFR mutation status had a 62% response rate." (PMID 18283321, 2008). "The populations with higher responses to gefitinib (females, non-smokers and patients with an adenocarcinoma histology) also have higher incidences of EGFR mutations." (PMID 18985035, 2008). "The incidence varies from one report to another, but EGFR mutations tend to be more common among patients with an adenocarcinoma histology and among non-smokers." (PMID 18985035, 2008). "Twenty-six (44%) of the adenocarcinoma patients had EGFR mutations, whereas only three (3.5%) nonadenocarcinoma patients had EGFR mutations." (PMID 18283317, 2008). "In the present study, EGFR mutations were detected in 16 out of 40 (40%) female never smokers with adenocarcinoma who underwent the screening process, and 14 out of these 16 patients (88%) achieved a response after undergoing gefitinib therapy." (PMID 18283321, 2008). "The frequency of these characteristics was higher among the patients with EGFR mutations who were actually registered; namely, 18 patients (64%) were women, 27 (96%) had adenocarcinoma and 19 (68%) had never smoked." (PMID 18283321, 2008).
adenocarcinoma (continued). "EGFR mutations were predominantly found in female subjects, nonsmokers, adenocarcinomas, and Japanese patients." (PMID 17325698, 2007). "Kaplan–Meier curves indicated significantly longer survival in patients with favourable PS (P<0.0001), in patients with adenocarcinoma histology (P<0.0001), in never-smokers (P<0.0001), and in patients with EGFR mutations (P<0.0001)." (PMID 17387341, 2007). "In a log-rank test, survival was significantly better in females, patients with adenocarcinoma, never-smokers, favourable performance status (PS) and patients with epidermal growth factor receptor (EGFR) mutation." (PMID 17387341, 2007). "Response rate was significantly higher among females, patients with adenocarcinoma histology, never-smokers and patients with the EGFR mutation." (PMID 17387341, 2007). "There have been several reports of clinical factors associated with EGFR mutations, and per the univariate analysis, mutation frequency is high in patients of East Asian ethnicity, females, never-smokers and adenocarcinomas." (PMID 17387341, 2007). "For example, when selecting patients with adenocarcinoma and smoking >20 pack-years, 15 of the 38 patients with EGFR mutations (39%) would be missed, whereas 13 of the 62 patients without EGFR mutations (21%) would be mistakenly included." (PMID 17106442, 2006). "Some clinical studies are trying to select patients to gefitinib treatment by clinicopathologic features of adenocarcinoma and non-smoker without testing EGFR mutations." (PMID 17106442, 2006). "We examined the overall survival in relation to EGFR mutations in patients with adenocarcinoma who did not receive gefitinib treatment." (PMID 16552419, 2006). "Interestingly, sensitive cells, especially in the adenocarcinoma cell lines, had more Akt phosphorylation with EGFR phosphorylation than resistant cells in serum-containing conditions (Chi-square test: p = 0.034: total, p = 0.0114: in adenocarcinoma)." (PMID 17150102, 2006). "The H358 adenocarcinoma cell line harbours a K-Ras mutant and no EGFR mutations, yet our predictor and data of others identify this cell line as sensitive to EGFR inhibition." (PMID 17096850, 2006). "We analysed the mutations of K-ras codon 12 in patients with adenocarcinoma, and detected a mutation in 29 cases (9.0%), but none of them had the EGFR mutations." (PMID 16552419, 2006). "Since all the Moffitt and Duke tumors were of adenocarcinoma histology, a known clinical predictor of benefit to EGFR TKI, it is possible that the genomic predictor may accurately classify sensitivity in this group of tumors." (PMID 17096850, 2006). "In patients with adenocarcinoma, the mutation rate of EGFR in patients who were never smokers, in patients who had less than a 10 pack-year of smoking index, and in patients who had a 10–20 pack-year of smoking index was 57.4, 66.7, and 56.5%, respectively." (PMID 16552419, 2006). "Previous studies have demonstrated EGFR mutations to be associated with adenocarcinoma, well differentiation, female gender, and never smokers." (PMID 16552419, 2006). "High incidence of harbouring EGFR mutations in nonsmokers adenocarcinoma well-explains this predilection on pathological findings." (PMID 16052218, 2005). "Although EGFR mutations were reported to occur with high frequency in nonsmoking Japanese adenocarcinoma patients, the exact nature has not been fully elucidated." (PMID 16052218, 2005). "The histological subtype of adenocarcinomas according to WHO classification did not correlate statistically with their EGFR incidence of mutations." (PMID 16052218, 2005). "Furthermore, although patients with adenocarcinoma in this investigation were less likely to express EGFR than other histological subtypes, all objective responses were observed in patients with adenocarcinoma." (PMID 15187994, 2004). "EGFR was detected in 66% of the adenocarcinomas analysed with LBA." (PMID 1457340, 1992).
adenocarcinoma (continued). "All patients had EGFR-mutated adenocarcinoma, and the majority (80.4%) were nonsmokers." (PMID 41333366, 2025). "Similar to other studies, EGFR mutations were more frequent in adenocarcinomas and non-smokers." (PMID 41327362, 2025). "The clinical features of lung cancers carrying mutations in the echinoderm microtubule associated protein-like (EML4)-ALK fusion gene include mild or never smoking, younger age, adenocarcinoma with an alveolar pattern or impression ring adenocarcinoma, and lack of EGFR or KRAS mutations." (PMID 40136367, 2025). "However, enteric adenocarcinomas occasionally show focal TTF-1 expression and EGFR mutations, suggesting that some enteric adenocarcinomas may be phenotypically altered from TRU-type adenocarcinomas." (PMID 38710944, 2025). "Additionally, combining immunotherapy with other treatments, such as chemotherapy and antiangiogenic therapy, could be a future direction for SCLC treatment, as it has shown potential in the treatment of EGFR-mutant adenocarcinoma and classical SCLC." (PMID 40507907, 2025). "Notably, our cohort was composed predominantly of non-smokers with adenocarcinoma, consistent with the higher frequency of EGFR mutations in Asian populations." (PMID 41142757, 2025). "The recognition of SCLC transformation as a recurrent resistance phenotype has prompted investigation into its biological basis, particularly whether EGFR-mutant adenocarcinoma and SCLC derive from a shared progenitor population capable of lineage plasticity under therapeutic pressure." (PMID 41516316, 2025). "However, BM was common in female patients (p = 0.015), those who had never smoked (p < 0.001), and patients with adenocarcinoma histology (p = 0.003), EGFR activating mutations (p = 0.013), and bone metastasis (p < 0.001)." (PMID 38256412, 2024). "Interestingly, a recent retrospective study involving 67 patients indicated that transformed SCLCs respond more favorably to taxanes compared to de novo SCLCs but displayed resistance to checkpoint inhibitors, mirroring the behavior of typical EGFR-mutant adenocarcinomas." (PMID 38329598, 2024). "Whilst the regulation of EGFR activity by sortilin seems to be the most plausible explanation behind this, given that EGFR signalling in the lung has more important clinical significance for adenocarcinomas, it can be considered highly probable that more pathways are involved." (PMID 38893272, 2024). "Adenocarcinoma cases had a higher prevalence of SNVs, CNVs, and/or fusions/rearrangements in 28 genes including therapy-associated genes such as KRAS (37.5% vs 4.6%), EGFR (17.1% vs 1.3%), BRAF (5.2% vs 1%), ERBB2 (1.8% vs 0.8%), RET (0.9% vs 0.3%), and ROS1 (1.2% vs 0.1%)." (PMID 39664186, 2024). "EGFR mutations were more common in adenocarcinoma (91.7%) and associated with female non-smokers." (PMID 39429333, 2024). "Based on local routine histology reports, there was a slightly higher percentage of patients with adenocarcinoma in arm B compared to arm A. Information about routine testing of EGFR mutation was available for 59 of the 71 adenocarcinomas, with no detected EGFR mutation." (PMID 39148905, 2024). "Likewise, chemoresistance and tumorigenicity are one of the key characteristics of CSCs, their assessment was carried out using both in vitro and in vivo experiments in three distinct adenocarcinoma cell lines expressing or not EGFR mutations." (PMID 39304747, 2024). "This may be explained by EGFR mutations, which were observed more frequently in adenocarcinoma in never‐smokers than in ever‐smokers." (PMID 39082888, 2024).